GPX1 (glutathione peroxidase 1)
Diseases named in the same sentence as GPX1 in open-access papers (continued):
Sharing a sentence is not in itself a finding about the gene and the disease.
cancer (continued). "Among the last group the most applicable ones are GPX1, the overexpression of which by itself has different effects on cancer initiation and development in different experimental systems (cancer initiation; promotion; and suppression)." (PMID 36552527, 2022). "The other mammalian selenium-containing proteins, such as selenium-binding protein and glutathione peroxidase 1 (GPX1), also play important roles in cancers." (PMID 36386843, 2022). "Many studies have also emphasized the critical role of GSH and GPX-1 in the development of cancer resistance." (PMID 35799889, 2022). "Some genes were expressed at similar levels in different types of cancer, including GPX1, GPX4, TXNRD1, TXNRD2 and TXNRD3." (PMID 33706760, 2021). "Our study found that GPX1 gene expression tended to be elevated in most cancers, and the results of survival and tumor stemness analyses suggested that the GPX1 gene plays different roles in different types of cancer." (PMID 33706760, 2021). "GPx1 is a key enzyme in cellular redox regulation; its role in cancer initiation, progression, and treatment has been diversely discussed in the literature." (PMID 34299253, 2021). "With this strategy in mind, we have examined novel pentathiepins not only with regards to their potential to inhibit the GPx1 but also in the context of cytotoxicity in cancer cells." (PMID 34299253, 2021). "A previous study also revealed that GPX1 inhibits EMT progression in cancer and plays an anticancer role." (PMID 35178395, 2021). "Increased GPX1 expression was reported in the head and neck, gastric, and hepatic and prostatic malignancies." (PMID 34943522, 2021). "First, we assessed the potential of the compounds to inhibit the isolated GPx1 and then screened for cytotoxicity across a panel of 14 human cancer cell lines under normoxic and hypoxic conditions." (PMID 34299253, 2021). "We assessed GPX1 gene expression level as it was thought to be related to pathogenicity of cancer in a variety of malignant tumors." (PMID 34943522, 2021). "Pentathiepins are polysulfur-containing compounds that exert antiproliferative and cytotoxic activity in cancer cells, induce oxidative stress and apoptosis, and inhibit glutathione peroxidase (GPx1)." (PMID 34299253, 2021). "Collectively, we concluded that GPx1 functions as the master regulator of the ASK1-JNK-cFLIP-caspase-8 axis in apoptosis pathways via stimulation-dependent interaction with TRAF2 in cancer cells." (PMID 34158609, 2021). "The MTT viability assay was then used to evaluate the effect of a GPx1 knockout in cancer cells towards the cytotoxicity of anticancer drugs." (PMID 33353055, 2020). "In different immune cell-derived cancer cell lines, it has been shown that GPx4 and GPx1 act as important inhibitors of cellular 5-LOX activity." (PMID 31765890, 2020). "For this purpose, a GPx1 knockout of the near-haploid human cancer cell line HAP-1 was generated and compared to the native cell line with regards to morphology, growth and metabolic rates, and oxidative stress defenses." (PMID 33353055, 2020). "In this proof-of-concept study, we used a GPx1 knockout cell line, obtained by a CRISPR-Cas9 deletion of the only GPX1 gene in HAP-1 haploid human cancer cells, to analyze for differences in potency of widely used anticancer drugs to the parental line." (PMID 33353055, 2020). "Due to its antioxidant properties, GPx1 is thought to be highly effective in preventing the ROS-mediated initiation of cancer." (PMID 32571353, 2020). "Interactions between the genotypes of GPX1 and SOD2, the gene encoding manganese superoxide dismutase, another antioxidant protein, also impact the regulation of proteins implicated in cancer progression." (PMID 32806741, 2020). "Most studies with cancer cells generally report the methylation of selenoproteins like glutathione peroxidase 1 and 3, methionine sulfoxide reductase B1 and selenium binding protein 1 in the promoter region." (PMID 32722369, 2020).
cancer (continued). "To confirm the accuracy of the cancer database, we examined the expression of GPX1 in RCC cells and tissues, and the results were consistent with the database predictions." (PMID 31844035, 2019). "Altered expressions of GPXs enzymes, especially GPX1, have been described in a variety of human cancers." (PMID 31032363, 2019). "GPx1 expression in cancer tissue (red line) was 44.4 ± 2.8% less than the average values detected in healthy tissue (black line) (p < 0.001, range + 27 to − 74%)." (PMID 29371830, 2018). "Given the cumulative data indicating possible roles of both SELENBP1 and GPX1 in cancer development and/or outcome, the interaction of these two selenium-associated proteins was investigated in several model systems." (PMID 29535818, 2018). "In this study, changes in gene expression were observed for SELENOP, SELENOS, and TXNRD3 for all sample groups, while GPX4 was significant in the Irish cancers only and GPX1, SELENOH, and SELENON were differently regulated in the Czech CRCs." (PMID 30469315, 2018). "For each patient, two samples were tested for the presence of GPx1 and TrxR1: one sample from the healthy thyroid tissue and one sample from the cancer tissue." (PMID 29371830, 2018). "Taking all patients together, the densitometric analysis of the GPx1 expression showed a significant lower mean concentration in cancer tissue, compared to healthy tissue." (PMID 29371830, 2018). "Glutathione peroxidase-1 (GPx-1) is a crucial antioxidant selenoenzyme that regulates cellular redox level, thus becomes a potential target in cancer treatment." (PMID 28273930, 2017). "As a selenoprotein sensitive to body selenium fluctuation, GPX1 likely interacts with SBP1 in the response of cancer cells to supplemental selenium or changes in redox status." (PMID 27404728, 2016). "GPx1 overexpression also suppresses the intracellular ROS and therefore exhibits a critical anti-cancer role of GPx1 in carcinogenesis." (PMID 27023612, 2016). "Activation of GPx1 results in imbalanced redox homeostasis and, more importantly, attenuates cancer cell proliferation and tumor growth." (PMID 27023612, 2016). "Therefore the GPX1 gene polymorphism may increase the risk of cancer induced oxidative DNA damage." (PMID 25436036, 2014). "Expression of GPX1 in the group of poorly differentiated carcinomas and the group with more than one lymph node involved was significantly lower than that in the groups with well or moderately differentiated carcinoma and no lymph node involvement." (PMID 24228025, 2013). "The genes categorized into “cancer” group by IPA biofunctions analysis were GPX1, HDAC7, PSME2, MED6, GOLPH3 and MST4 (p<0.05)." (PMID 22438889, 2012). "Dual targeting of GPX4 and GPX1 presents a potent anti‐cancer strategy." (PMID 40259435, 2025). "Combining GLS1 or GPX1 inhibitors with a GPX4 inhibitor synergistically suppresses cancer growth." (PMID 40259435, 2025). "Furthermore, the combination of ML‐210 and ED‐71 also synergistically inhibited tumour growth (synergy index > 10), as the simultaneous inhibition of GPX4 and GPX1 disrupts their compensatory responses, offering a promising strategy for cancer therapy." (PMID 40259435, 2025). "Rather than inhibiting antioxidant enzymes directly, enhancing SeP may reduce hepatic selenium retention and thereby limit the synthesis of selenoproteins such as GPx1 and GPx4, which support cancer cell survival under oxidative stress." (PMID 40818321, 2025). "To address this, we explored whether simultaneous inhibition of GLS1, GPX4 and GPX1 could synergistically inhibit cancer cell growth." (PMID 40259435, 2025). "Furthermore, the levels of GPx1 have been observed to exhibit a direct correlation with the progression to advanced metastatic cancer, underscoring its potential role in cancer biology." (PMID 39839762, 2024). "We will focus on GPX4 and GPX1 because of their important roles in cancer." (PMID 39061847, 2024).
cancer (continued). "The translocation of GPX1 to the nucleus in cancer cells under oxidative stress may facilitate the antioxidant functions of GPx-1." (PMID 39728443, 2024). "However, silencing GPX1 induced a mesenchymal phenotype and conferred resistance to gemcitabine in PDAC, paradoxically suggesting a potential anticancer role of GPX1 in certain cancer types or contexts." (PMID 39061847, 2024). "Activated GPx1 can protect cancer cells from ROS and anticancer agents." (PMID 38398797, 2024). "Notably, an overabundance of GPx1 has been demonstrated to shield cancer cells from the potent oxidizing effects of anticancer therapeutics." (PMID 39839762, 2024). "GPx1 may play opposite roles in different types of cancers and can act as a tumor suppressor or promoter." (PMID 39125992, 2024). "Overexpression of the GPX1 gene has been widely reported in human cancers." (PMID 37692064, 2023). "Combining GPX1 inhibitor treatment with photodynamic therapy can generate synergistic anti-tumour effects by enhancing oxidative stress, accumulating ROS and inducing apoptosis in cancer cells." (PMID 37446063, 2023). "The activation of GPX1 allowed the intense oxidative stress in the tumor microenvironment to be reduced, which allowed cancer cells to survive, proliferation, malignant transformation, and metastasis of cancer cells." (PMID 37606338, 2023). "Using this method, the Gpx-1 protein level was determined in cancer cell lines in vitro." (PMID 37242524, 2023). "However, the aberrantly increased expression levels of GPX1 in many cancers were closely related to tumorigenesis and progression." (PMID 37606338, 2023). "Moreover, by using the immunogold labelling method, the intracellular localisation of Gpx-1 was detected within the cells of cancer tissues." (PMID 37242524, 2023). "In cancer cells, black granules indicating the presence of Gpx-1 were detected in the cytoplasm." (PMID 37242524, 2023). "On the other hand, there is still no general agreement on how is GPX1 Pro198Leu gene polymorphism related to cancer risk." (PMID 36676755, 2023). "The increased expression of this protein in cancer cells suggests that Gpx-1 may play an important role in carcinogenesis and disease progression." (PMID 37242524, 2023). "Additionally, the FDA approved arthritis treatment auranofin (AF, Ridaura®) is known to inhibit the selenoproteins thioredoxin reductase (TXNRD1) and GPX1 with emerging potential as an anti-cancer agent." (PMID 37244126, 2023). "However, GPX1 has a complex dichotomous role as a potential tumor suppressor or promoter in different cancers, given that it is involved in various signaling pathways to regulate multiple tumor-related biological behaviors." (PMID 37862109, 2023). "However, aberrantly increased expression of GPX1 in many cancers is closely connected to tumorigenesis and progression including LC." (PMID 37606338, 2023). "Moreover, aberrant expression of GPX1 in multiple cancers is closely related to oncogenesis and cancer progression." (PMID 35626163, 2022). "However, GPX1 is abnormally overexpressed in most types of cancer and acts as a tumor promoter by regulating the proliferation, invasion, migration, apoptosis, immune response, and drug sensitivity of tumor cells." (PMID 35626163, 2022). "Hence, many studies are devoted to exploring GPX1 inhibitors and their applications for cancer therapy." (PMID 35626163, 2022). "Current studies collectively indicate that high expression levels of GPX1 may have different prognostic values for different types of cancers." (PMID 35626163, 2022). "Although, intuitively, higher GPX-1 activity could suggest better protection against oxidative stress and thus cancer, the relationship is complex." (PMID 35215475, 2022). "Oppositely, the CAT and GPx-1 levels are strongly elevated in cancer cells that undergo TIS." (PMID 36230727, 2022).
cancer (continued). "Our work may deepen the understanding of the critical clinical values and future directions of GPX1 as a potential prognostic biomarker and novel cancer therapeutic target." (PMID 35626163, 2022). "To date, eight different GPx family members (GPx1-GPx8) have been identified, and recent studies have demonstrated that several members of the GPx family play a crucial role in resistance to anti-cancer therapies by altering levels of oxidative stress." (PMID 35892591, 2022). "In addition, understanding the molecular mechanisms and functional networks responsible for the role of GPX1 in carcinogenesis is critical for developing novel strategies for precision cancer therapy." (PMID 35626163, 2022). "GPX1 is considered to serve as an oncogene or tumor suppressor in different cancers." (PMID 34922551, 2021). "Interestingly, three proteins of the proteins found in this study (RNF213, RPL8, GPX1) were also discovered as differentially expressed in a study in which platelet mRNA of cancer patients was compared to that of healthy individuals." (PMID 34361002, 2021). "Glutathione peroxidase 1 (Gpx1) and peroxiredoxin 2 (Prdx2) belong to the thiol peroxidase family of antioxidants, and have been studied for their antioxidant functions and roles in cancers." (PMID 34679770, 2021). "Drugs with similar inhibitory effects on GPX1 activity might therefore also help shrink tumors in human cancer patients." (PMID 34158609, 2021). "Many authors have reported that GPX1 can perform opposing functions in various cancers." (PMID 34943522, 2021). "Not only the inhibition of the GPx1 renders these polysulfur structures an interesting class of compounds; their great capability to prevent the proliferation of cancer cells and the induction of apoptosis as a controlled form of cell death labels them as potentially useful anti-tumor treatments." (PMID 34299253, 2021). "Moreover, an influence of selenoprotein polymorphisms on the risk of breast (Gpx1, SelF, SelP) or colorectal (Gpx4, TrxR1, and TrxR2, SelP, SelF, and SelS) cancer was also found, which could indicate their important role in the etiology of these types of cancer." (PMID 34068374, 2021). "Considering the data described earlier, GPX1 may have a protective or injurious biological function depending on the type of malignant tumor." (PMID 34943522, 2021). "By helping cancer cells eliminate potentially harmful hydrogen peroxide, the role of GPX1 as the most abundant GPX form might be contradictory." (PMID 33953831, 2021). "Previous studies revealed superoxide dismutase (an antioxidant) activity facilitated anoikis resistance in ECM detached cancer cells, so we sought to investigate the effect of metformin treatment on two antioxidant families glutathione peroxidase 1–3 and superoxide dismutase 1–3." (PMID 35054435, 2021). "This conclusion is consistent with previous findings, and so the role of the GPX1 gene in cancer might need to be analyzed while considering specific types of cancer in order to identify the underlying mechanism." (PMID 33706760, 2021). "Research on this matter is limited, considering that GPX1 serves as an oncogene in cancers." (PMID 35178395, 2021). "Gpx1 has also been known for its significant roles in cancer." (PMID 34679770, 2021). "Thus, our study demonstrates the GPx1-centered signaling module determining cell fate in cancer cells." (PMID 34158609, 2021). "Thus, the in vivo study validated the findings showing that GPx1 serves as a redox shield against apoptotic insults in tumor-residing cancer cells." (PMID 34158609, 2021). "Considering that lncRNAs can participate in the etiology and progression of cancers via ceRNA networks, we assumed that there might be some lncRNA upstream of miR-419-5p-miR-214-3p/GPX1 axis." (PMID 32808668, 2020). "However, to the best of our knowledge this is the first report linking the potentiation of lomustine cytotoxic activity to the lost expression of GPx1 in cancer cells." (PMID 33353055, 2020).
cancer (continued). "It is known that in some types of cancer GPx1 is upregulated, e.g., adult acute leukemia, thyroid tumors or urothelial carcinoma, whereas other types showing a downregulation such as adult chronic leukemia, breast cancer cell lines, gliomas or renal cell carcinoma." (PMID 33353055, 2020). "Previous researches have reported the oncogenic role of GPX1 in several carcinomas." (PMID 32808668, 2020). "It was shown that GPx plays an important role in cancer development, and that a loss of heterozygosity (LOH) at the GPx1 locus and changes in GPx expression may be the early events in cancerogenesis." (PMID 30978928, 2019). "Upregulation of GPX1 has been reported in several major cancer types, such as lung and breast." (PMID 31032363, 2019). "Normalization with PGK1 and GPX1 might have diluted the tumorous heterogeneities among cancer patients." (PMID 29915691, 2018). "Moreover, to determine the effect of GPx1 on the energy requirements for highly proliferating cancer cells under glucose starvation conditions, we then analyzed ATP production." (PMID 30538220, 2018). "Furthermore, the difference of the GPx1 expression between healthy and cancer tissue, measured for each patient, was statistically significant for 16 of the 20 patients studied." (PMID 29371830, 2018). "Moreover, the decrease in antioxidant enzymes GPx1 and TrxR1 in cancer tissue indicates that the antioxidant system in cancer cells is unable to adequately counteract the effects of the free radicals." (PMID 29371830, 2018). "Although this pilot study had not the objective of associating the genetic variation in selenoprotein genes with risk of diseases, it should be noted that the polymorphisms mentioned here, mainly GPX1 rs1050450 and GPX4 rs713041, have been associated with cancer risk." (PMID 27164132, 2016). "Recent study suggests that glutamate dehydrogenase 1 (GDH1), a mitochondrial enzyme critical for redox homeostasis, is shown to control the intracellular levels of α-ketoglutarate and further metabolite fumarate, which binds to and activate GPx1 in cancer cells." (PMID 27023612, 2016). "So far, it has been shown that changes in the activity of the GPX1, GPX2, and GPX3 isoforms may be associated with the development of cancer." (PMID 26682223, 2015). "However, the SNP effect seemed to be preserved among cancer cases, with Pro/Pro cancer homozygotes having the highest GPx1 activity as compared to other groups." (PMID 26446998, 2015). "The GPX-1 gene has been found to be a frequent LOH locus in cancers of the lung, breast, and ovary." (PMID 24228025, 2013). "GPx1 is postulated to prevent initiation of cancer through ROS-mediated DNA damage whereas GPx4 could inhibit growth of established tumors." (PMID 23153283, 2012). "Some epidemiologic studies have correlated low GPX1 activity or particular GPX1 polymorphisms with enhanced risk of cancer, although these correlations have not been consistently observed in all populations." (PMID 17156480, 2006). "It's expression may be regulated in a contrasting pattern to GPX1 in certain cancer systems and disruption of its expression may reverse the phenotype and carcinogenicity of lung cancer cells." (PMID 17156480, 2006). "Hence, the role of GPX1 in oncogenesis or cancer progression is worthy of investigation." (PMID 40346054, 2025). "The ambiguous role of GPx1 in cancer may be explained by the suppression of oxidative stress-induced inflammation and mutagenesis (DNA damage), but also by the blockade of apoptotic cell death, which in turn may result in enhanced survival of cancer cells (Brigelius-Flohé and Kipp 2009)." (PMID 38483584, 2024). "Meta-analyses do not provide a clear answer as to whether the GPX1 Pro198Leo polymorphism can promote cancer susceptibility." (PMID 37446063, 2023). "In cancer, GPX1 and GPX3 are tumor suppressors, while GPX2 may have dual roles in tumorigenesis." (PMID 36443446, 2022).